CD4 (CD4 molecule)
Diseases named in the same sentence as CD4 in open-access papers (continued):
Sharing a sentence is not in itself a finding about the gene and the disease.
tumor (continued). "The results showed that, in tumor tissues, the proportions of total T cells (28.88% vs. 2.93% vs. 5.16%) and the CD4+ T cell (89.23% vs. 36.97% vs. 34.33%) subset were significantly higher in the F1/F3-treated mice group compared with both the PBS- and P3-treated mice." (PMID 40573908, 2025). "This study not only confirms and extends pancancer observations but also uniquely reveals a lymph node origin for stem-like CD4+ T cells that give rise to tumor-infiltrating Tfh cells, underscoring the importance of spatial and clonal relationships in shaping immune responses in cancer." (PMID 40634636, 2025). "Some CD4 T cells are also capable of directly killing HLA class II-expressing tumor cells." (PMID 40151616, 2025). "CD4+ T cells have been well-regarded as “helper” cells in activating the cytotoxicity of CD8+ T cells for effective tumor eradication, while few studies have focused on whether CD8+ T cells regulate CD4+ T cells." (PMID 40277945, 2025). "In AE tumours there was higher clonal overlap between CD4 naïve and Tfh T cells." (PMID 39915477, 2025). "Conversely, chemokines may also participate in anti-tumor immune responses by recruiting CD4-positive T cells, CD8-positive T cells, and natural killer cells, enabling these effector cells to suppress tumor growth." (PMID 41259383, 2025). "The results demonstrated that CD68 expression has significant negative relation with tumor purity and B cell, significant positive correlation with tumor-infiltrating levels of CD4+ T cell, CD8+ T cell, macrophage, myeloid dendritic cell and cancer associated fibroblast in COAD." (PMID 40918116, 2025). "Tumor-infiltrating CD4+ and CD8+ T lymphocytes were quantified via immunohistochemistry." (PMID 40299475, 2025). "Moreover, iBMDMs treated with IFN-α prior to orthotopic co-injection with PDAC tumor cells markedly decreased the infiltration of CD4+/CD8+ T cells and increased the percentage of exhausted T cells in the TME." (PMID 40098954, 2025). "Overall, these results might suggest that the long neoantigen peptide induced neoantigen-specific CD4+ T cells and contributed to tumor shrinkage." (PMID 40248703, 2025). "We analyzed 1357 CD4+ T cells from tumor and adjacent tissues." (PMID 41008548, 2025). "Moreover, the residual tumor cells from mice given M002-treated CD4+ T cells had significantly higher levels of MHCII than the other two groups." (PMID 39885128, 2025). "UMAP dimensionality reduction analysis revealed the presence of multiple distinct cell clusters within the tumor ecosystem, which were annotated as malignant cells, macrophages, tumor-associated fibroblasts (CAFs), CD8 T cells, CD4 T cells, NK cells, endothelial cells, and T cells." (PMID 40652057, 2025). "Similarly, EVs from LGG ATCC 53103 synergized with anti-PD-1 immunotherapy, fostering a higher infiltration of MHC II+ dendritic cells, CD8+, and CD4+ T-cells into the tumor." (PMID 41301527, 2025). "PD-1 can also be expressed on tumor-infiltrating lymphocytes (TILs), while tumor cells may express PD-L1 at varying levels, contributing to the inhibition of CD4+ and CD8+ T-cell activation and the apoptosis of antigen-specific T-cell clones." (PMID 40227645, 2025). "Additionally, combining this treatment with Alb-IFNβ increased CD8+ and CD4+ T cell infiltration in the tumor microenvironment while reducing PD-1 expression on TILs and regulatory T cells, thereby enhancing the overall immune response." (PMID 40539072, 2025). "Similarly, Akkermansia muciniphila restores PD-1 blockade efficacy by recruiting CCR9+CXCR3+CD4+ T lymphocytes into the tumor microenvironment in an IL-12-dependent manner." (PMID 40129929, 2025). "In addition, OV infection can induce tumor cells to undergo immunogenic cell death, stimulate the recruitment of specific immune cells, such as CD4+ and CD8+ T cells, and then induce T cells to attack uninfected tumor cells." (PMID 40821119, 2025).
tumor (continued). "Consistent with reported PDT effects, the subsequent DAMPs release from light-irradiated tumorcells promoted dendritic cell maturation for antigen presentationand further induced tumor antigen-specific CD4+ and CD8+ T-cell responses, thus achieving photosensitive cancer immunotherapy." (PMID 39862206, 2025). "Finally, CD4+ T cell depletion resulted in a strong upregulation of PD-1 on tumor-infiltrating CD8+ T cells and defects in the generation of granzyme B+ cytotoxic CD8+ T cells upon treatment." (PMID 40460830, 2025). "Lastly, P17 was shown to improve CD4+ T‐cell proliferation in mice implanted with EG.7‐OVA tumours." (PMID 40245195, 2025). "On the other hand, Tregs, a special subset of CD4+ T cells, may suppress anti‐tumour immune responses by secreting immunosuppressive cytokines such as IL‐10 and TGF‐β." (PMID 40785042, 2025). "The enriched resting memory CD4+ T cells might be functionally exhausted, failing to effectively initiate anti-tumor immunity." (PMID 41286896, 2025). "In addition to these effects, the presence of M1 macrophages and CD4+ T cells play a crucial role in inhibiting tumor growth." (PMID 39927632, 2025). "The immunosuppressive function of mregDCs has been extensively documented in various cancers, where they exacerbate tumor progression by inhibiting effector CD4/CD8T cells while promoting Treg cell functions, but their regulatory functions in AA pathogenesis has not been studied." (PMID 41346489, 2025). "A previous study described that KLF5 deletion could promote anti‐tumor immunity by enhancing the proliferation and function of CD4+ and CD8+ T cells." (PMID 39720765, 2025). "The primed CD4+ Th2 cells are drawn back to the tumor by Th2 chemokines (TARC and MDC)." (PMID 40453074, 2025). "Expanding on this, we conducted proteomic analyses to examine the TME-specific changes induced by LDRT, revealing elevated levels of Granzyme B, MIP1α, and CD137 (4-1BB) within tumor-infiltrating CD4 + T cells, signifying enhanced activation and effector functionality." (PMID 39881333, 2025). "Moreover, neutrophils infiltrating the lung tumor microenvironment express high levels of MPO, which suppresses the anti-tumor functions of both CD4+ and CD8+ T cells and promotes tumor progression." (PMID 41254689, 2025). "Notably, despite transient CD3- or continuous CD4-depletion, a specific immune response and tumor control were still achieved through vaccination with pNGVL4a-CRT/E7(detox)." (PMID 40533862, 2025). "Besides, human NSCLC cells, including tumor cell lines and primary tumor cells from clinical patients, can efficiently drive metabolic adaptation of human CD4 + T cells, directing differentiation of regulatory T cells while suppressing effector T cells." (PMID 39901294, 2025). "In addition, we stained for tumor infiltrating lymphocytes (TILs): CD4+ T helper cells, CD8a+ CTLs, and B220+ B cells." (PMID 39808498, 2025). "Upon recognition of tumour‐associated antigens presented via MHC‐II, CD4+ T cells can differentiate into distinct effector subsets, including Th1 cells that promote cytotoxic activity through IFN‐γ and TNF‐α production, and Tfh cells that support B cell–mediated humoral immunity." (PMID 40673641, 2025). "However, recent studies have shown that the increased expression of endogenous TLR3 in tumor cells can improve the responses of CD4+ Th1 and CD8+ cytotoxic T cells, and is used to improve immunotherapy by innate immunity in the TMEt." (PMID 40406122, 2025). "The restoration of functional CD4 populations by ART coupled with increased CRT-mediated tumor killing may provide a synergistic role in WLWH." (PMID 40099965, 2025). "A higher tumor grade positively correlated with CD69+CD103+CD4+ T cells in the tumor." (PMID 40361474, 2025). "Additionally, MWCNT-based nanocomposites increased the infiltration and maturation of DCs, CD8+, CD4+ T cells, macrophages, and NKs in tumours treated with ox-MWCNTs–hypothermia combination therapy." (PMID 40710305, 2025).
tumor (continued). "The hypothesis that the lack of toxicity is due to T28zT2 T cells forming an immunological synapse with tumor cells via NKG2D is indicated on the observation that CD4+ T28zT2 T cells upregulated NKG2D in tumors and is speculative." (PMID 40107245, 2025). "Looking forward, the model’s utility could be further expanded by incorporating additional experimental data, particularly for longer peptides relevant to MHC class II presentation and CD4+ T-cell responses, which play critical roles in anti-tumor immunity." (PMID 40872950, 2025). "Activated CD4 memory T cells state play a pivotal role in tumorigenesis, and these cells are capable of recognizing and attacking tumor cells, thereby playing a role in immune surveillance and tumor clearance." (PMID 40352921, 2025). "Using multiplex flow cytometry, we demonstrate that synergistic treatment increased populations of CD8+, CD4+ tumor infiltrating lymphocytes and a shift from monocytic myeloid-derived suppressor cells (mMDSC) to granulocytic myeloid derived suppressor cells (gMDSC)." (PMID 40091830, 2025). "Interestingly, the decrease in tumor CD4+ Tregs was also seen with IGRT monotherapy and, to a lesser extent, with IGRT plus TAT." (PMID 40813233, 2025). "Furthermore, immunohistochemistry (IHC) analysis demonstrated that the ratio of CD4+ T cells was reduced in TMZ-treated tumor sections, whereas the ISP-I-treated group exhibited an opposite effect." (PMID 40809457, 2025). "Naive CD4+ T cells play a crucial role in shaping tumor immune responses." (PMID 40427030, 2025). "Hence, the study of these accessible cells in blood provides a broader representation of the antigenic specificities of intratumoral CD4+ T cells, including those that recognize tumor antigens." (PMID 40299576, 2025). "Furthermore, we aimed to explore the immune microenvironment in these patients by assessing immune cell infiltration, particularly CD4+ T cell density, in various tumor regions." (PMID 41212769, 2025). "Most CD4+ T cells in the tumor had an activated phenotype, with more than 60% expressing PD-1." (PMID 40196575, 2025). "Th2-polarized CD4+ T cells responding to TSLP played a seminal role in tumor suppression in vivo." (PMID 39744942, 2025). "Notably, some patients exhibited CD4+ T cell activation and differentiation into memory phenotypes, enhancing their anti-tumour response." (PMID 40005571, 2025). "Their findings revealed that MyD88 promotes the recruitment and activation of various immune cells, including M1-like tumour-associated macrophages, neutrophils, dendritic cells, CD4+ and CD8+ T cells, NK cells, and NKT cells, within the tumour microenvironment." (PMID 40005571, 2025). "Moreover, CD4 T cells with cytotoxicity contribute to the tumor microenvironment by secreting cytokines such as IFN-γ and TNF-α, which enhance immune activation and disrupt immune suppression." (PMID 40959273, 2025). "Spatial analysis showed increased density of suppressive immune cells around tumor cells, increased exhaustion phenotype of both CD4 and CD8 T cells expressing chemokine CXCL13, and spatial microcomplex of endothelial and lymphocyte interactions within tertiary lymphoid structures." (PMID 39803458, 2025). "They increase the density of T cells in the tumor by activating CD4+ T cells." (PMID 41019045, 2025). "Tregs accumulate in tumors through three ways: circulating tTregs are recruited into tumor nodules; the conventional CD4+ Foxp3− (Tconv cells) are converted of into pTregs cells under the influence of tumor‐derived factors including TGF‐β; and tissue‐resident Tregs proliferate on site." (PMID 39979425, 2025). "There is high heterogeneity among CD4+T/CD8+T studies due to the type of tumor and whether it is combined with chemotherapy." (PMID 41244814, 2025).
tumor (continued). "While PD-1 expression in T cells (CD4+ and CD8 + ) resulted unchanged, I2-treated tumors revealed a reduced expression of PD-L1 in the monocytic myeloid-derived suppressor cell (M-MDSC) subset monocytes and in tumor-associated macrophages (TAM)." (PMID 39962052, 2025). "In CCA, mature CD83+ DCs are commonly found at the tumor periphery alongside CD4+ and CD8+ T cells, suggesting a role in bridging innate and adaptive immune responses, although their peripheral localisation may reflect immune exclusion." (PMID 41143064, 2025). "The lymphocytes associated with the tumor immune microenvironment (TIME) are represented by all major subpopulations, including: CD20+ B-cells, CD3+CD4+ helper T-cells, CD3+CD8+ cytotoxic T-cells and the forkhead box P3-positive (FOXP3+) regulatory T-cells (Tregs)." (PMID 40725022, 2025). "To uncover the optimal composition of a peptide vaccine we de-linked major histocompatibility complex (MHC) class II helper peptides from the capsid and formulated an efficient neo-antigen-specific vaccine, which showed the independence of CD4+ T cell response from tumor sequences." (PMID 40671675, 2025). "MFC tumor-bearing mice models were established, and mice were assigned to the following treatment groups: Control, Asparaginase + anti-PD-L1, Asparaginase + anti-PD-L1 + anti-CD4, and Asparaginase + anti-PD-L1 + anti-CD8." (PMID 41229436, 2025). "Similarly, tumor-infiltrating lymphocytes (TILs), particularly αβ T cells (CD4+ and CD8+), and their subpopulations are also reported for their considerable functional roles in TME." (PMID 41023740, 2025). "Activated CD4+ T cells can reconstitute the immune microenvironment and promote tumor clearance." (PMID 40145017, 2025). "Conventional CD4+ helper T (THC) cells also have a contributing role in anti-tumor immune response." (PMID 41008548, 2025). "Notably, hyperactive DCs can enhance anti-tumour immunity in aged mice by overcoming DC migratory defects and boosting CD4+ T-cell activity." (PMID 40730233, 2025). "Interaction between MHC class II on tumor cells and CD4+ tumor-infiltrating lymphocytes (TILs) may further contribute to immune evasion." (PMID 41303704, 2025). "Notably, the proportion of Foxp3+CD4+ Tregs was markedly decreased in the Se@MI-treated group, further supporting the notion that Se@MI reshapes the tumor immune microenvironment by mitigating immune suppression." (PMID 41246348, 2025). "More importantly, TAGAP expression was decreased in LUAD and overexpressed TAGAP could limit the tumor progress, thus increasing the toxicity and immune infiltration ability of CD4+ T cells." (PMID 39998561, 2025). "The partial rescue from CD8+ T cell depletion prompted us to deplete both CD4+ and CD8+ T cells, as CD4+ T cells might also mediate direct tumor control." (PMID 39540840, 2025). "In addition, selective pressure imposed by CD4 + T cell on tumor cells leads to elimination of HLA class II-positive tumor cells by cognate CD4 + T cells and thus outgrowth of HLA class II-negative tumor cells." (PMID 39928678, 2025). "The immune landscape is characterized by an increased presence of CD8+ T cells, decreased populations of CD4+ T cells, and significant expression of immune checkpoints that may inhibit their effective anti-tumor activity." (PMID 40599139, 2025). "Therefore, tumour elimination usually requires the coordinated actions of both CD4+ and CD8+ T cells." (PMID 40172096, 2025). "In addition, the DEGs of NK cells, CD8+ T cells, CD4+ T cells, and Treg cells between tumor and normal tissues were also performed." (PMID 40723292, 2025). "Furthermore, SUV39H2 inhibition significantly enhances oHSV-1 replication within tumor tissues and promotes CD4+ T and CD8+ T immune cell infiltration into the tumor microenvironment, ultimately improving the virus’s oncolytic efficacy." (PMID 40849299, 2025). "Concurrently, HIFU promotes CD4+/CD8+ lymphocyte infiltration into tumor tissues." (PMID 41367870, 2025).
tumor (continued). "However, an increased number of T cells (particularly CD4+ T cells) was detected in the spleen of 2015-treated tumor-bearing mice." (PMID 39820127, 2025). "CD4+ T cells can also exert direct cytotoxic effects on MHC class II-expressing tumor cells." (PMID 41374974, 2025). "XIST is more highly expressed in patients with high tumor and peritumoral CD4 inflammation." (PMID 40352941, 2025). "In a separate patient, we confirmed enhancement of tumor killing by circulating and intratumoral CD4+ T cells by E-cadherin blockade that is specific for KLRG1, and also MHC class II in agreement with our prior findings, and was not impacted by isotype control antibodies." (PMID 40299576, 2025). "In addition, tumor cells evade immune surveillance through various mechanisms, including suppression of naive B cell differentiation and activation of resting memory CD4 + T cells." (PMID 40833956, 2025). "However, the limited role of B cells and CD8 T cells in triple combination mediated tumor control suggests that CD4 T cells independently contribute to tumor surveillance." (PMID 40299790, 2025). "Among CD4+ subsets, Tregs generally promote immune suppression and tumor progression." (PMID 40534852, 2025). "Interestingly, CD8+ Interferon-stimulated genes (ISGs+) T cells, known for their potent anti-tumor properties, emerged as primary interactors with CD4+ CXCL13+ Tfh, CD8+ CXCL13+ T, and CD8+ Temra cells in the ICB-Rs." (PMID 40054456, 2025). "Additionally, we have also obtained single-cell TCRαβ sequences from expanded KLRG1+ and KLRG1– CD4+ T cells from PBMCs, and matched total CD4+ T cells from tumor, of 2 patients." (PMID 40299576, 2025). "In a preclinical study, the combination of JHU083 with an EGFR peptide vaccine (EVax) in homozygous EGFR‐mutant mice leads to enhanced tumor infiltration of CD8+ T cells and CD4+ Th1 cells with an increasing oxidative metabolism and improves tumor suppression compared with EVax monotherapy." (PMID 40959206, 2025). "Thus, accurately predicting the selection of neoantigens with appropriate length and number to optimize CD8+ and CD4+ T cell responses poses an additional challenge in achieving effective tumor immunotherapy." (PMID 40563603, 2025). "Resveratrol downregulated PD-1 expression on local CD8+/CD4+ T cells and promoted M1 macrophage polarization, which may contribute to resveratrol-mediated anti-tumor efficacy." (PMID 40940890, 2025). "Interestingly, the presence of both FAP + CAFs, T-cyts (CD8 +), T-regs (CD4 + FOXP3 +), and macrophages (CD68 +) above P75 (log-rank p = 0.016) at the tumor center was associated with worse CSS." (PMID 39751643, 2025). "Distinguishing among these possibilities has been difficult as the developmental course of NeoAg-specific CD4+ T cells responding to progressive tumor growth in vivo is largely unknown in terms of phenotype, magnitude, and TCR repertoire." (PMID 40196575, 2025). "Moreover, CD4+ T cell–depleted calcipotriol-treated WT mice showed a significant acceleration of tumor growth compared with calcipotriol-treated WT mice (P < 0.0001)." (PMID 39782693, 2025). "The modulation of tumor-infiltrating CD4+ T lymphocytes and changes in the ratio of regulatory T lymphocytes to CD8+ T lymphocytes, may also be relevant for immune modulation." (PMID 39425911, 2025). "In general, our results revealed the terminally activated and exhausted status of T cells in the tumour, when CD39+ CD4+ Tregs were increased in the marginal intestinal architecture, potentially contributing to the establishment of immunosuppressive environment and tumour progression." (PMID 39934971, 2025). "In addition, SCC tumours exhibited a higher frequency of CD4+ and CD8+ T cells co-expressing TIM-3 with PD-1, and also LAG-3 co-expressed more often with other checkpoint molecules on CD8+ T cells, suggesting a more exhausted immune state in SCC than in AC." (PMID 40639721, 2025).